TNFRSF1B (TNF receptor superfamily member 1B)
Diseases named in the same sentence as TNFRSF1B in open-access papers (continued):
Sharing a sentence is not in itself a finding about the gene and the disease.
mastitis (4 papers, 2016 to 2025). Inflammation of breast tissue during lactation or postpartum due to an obstructed duct or infection. "Some immune-related genes, such as ITGB6, MYD88, ADA, ACKR1, and TNFRSF1B, and their potential relationships with mastitis were highlighted." (PMID 27459697, 2016). "DEGS such as IL10, CCL5, IL1B, OSM, TNFRSF1B, IL7, and CCR3, among others, implicated in these pathways, may play a crucial role in the development of subclinical mastitis in Bactrian camels, though further analysis is needed to explore their potential functions." (PMID 40005880, 2025).
sarcoidosis (4 papers, 2012 to 2023). Sarcoidosis is a multisystemic disorder of unknown cause characterized by the formation of immune granulomas in involved organs. "TGFB2 and KDR variants were reported to be associated in a German cohort with an acute course of sarcoidosis and variants of TNFRSF1B are known to influence the response to anti-TNF therapy in sarcoidosis." (PMID 37621457, 2023).
endometrial cancer (3 papers, 2023 to 2025). Primary or metastatic malignant neoplasm involving the endometrium (mucous membrane that lines the endometrial cavity). "The marked upregulation of IL6R and TNF receptors (TNFRSF1A, TNFRSF1B) in cancer tissue compared to controls supports the notion that these cytokines and their signaling pathways are central to the development and aggressiveness of endometrial cancer." (PMID 40642843, 2025). "We detected a clear TNFRSF1B signal on CD8+ T cells on tumour sections from HGSOC, clear cell carcinoma, and endometrial carcinoma patients, but not in normal ovary tissue." (PMID 37712139, 2023).
esophageal cancer (3 papers, 2021 to 2024). A primary or metastatic malignant neoplasm involving the esophagus. "The TNFRSF1B c.587T>G genotype did not alter the responses to 5-fluorouracil and cisplatin and survival of patients with esophageal carcinomas, but its role in the CM outcome is still unknown." (PMID 38474115, 2024).
esophageal squamous cell carcinoma (3 papers, 2010 to 2023). Esophageal squamous cell carcinoma (ESCC) is a type of esophageal carcinoma (EC) that can affect any part of the esophagus, but is usually located in the upper or middle third. "Effects of TNFRSF1B polymorphisms on clinical response in Japanese patients with esophageal squamous cell carcinoma." (PMID 20646319, 2010). "In this study, genetic polymorphisms of TNFRSF1B gene were evaluated Japanese esophageal squamous cell carcinoma (ESCC) patients treated with the definitive 5-FU/CDDP-based chemoradiotherapy and their predictive values of prognosis or severe acute toxicities were assessed." (PMID 20646319, 2010).
HIV-1 infection (3 papers, 2025 to 2026). The type species of lentivirus and the etiologic agent of acquired immunodeficiency syndrome (AIDS). "Tnfrsf1b from R. norvegicus is involved in six distinct pathways such as “TNF signaling”, “cytokine–cytokine receptor interaction”, “HIV-1 infection”, and “ALS”." (PMID 40869347, 2025). "Phospholipase C, gamma-2 (PLCG2) was downregulated and tumor necrosis factor receptor superfamily member 1B (TNFRSF1B) was upregulated in vaccinated animals and enriched in HIV-1 infection." (PMID 41036542, 2025).
hyperandrogenism (3 papers, 2013 to 2025). Excessive secretion of androgens from the adrenal glands or gonads. "In humans, the p.M196R TNFRSF1B variant has been associated with hyperandrogenism and polycystic ovary syndrome in women." (PMID 23179634, 2013).
IgA nephropathy (3 papers, 2015 to 2024). "Our findings revealed that both target genes identified in gene expression analysis (C3 and TNFRSF1B) exhibited a significant upregulation of protein expression in the biopsies obtained from patients with IgA nephropathy when compared to control tissue." (PMID 38291238, 2024).
periodontitis (3 papers, 2022 to 2024). An acute or chronic inflammatory process that affects the tissues that surround and support the teeth. "During the inflammatory response of periodontitis, the lymphocytes, macrophage and neutrophils are regulated by expression of multiple genes, such as ARHGAP10, ARPC1B, DOCK1, FGF2/4, TNFRSF1B, NXT1, and AHR, all of which were identified in our analysis." (PMID 35491409, 2022). "In addition, our results showed the genes of TNFRSF1B and NPR3 were hypo-methylated in the periodontitis." (PMID 35491409, 2022).
allergic rhinitis (2 papers, 2020 to 2021). Inflammation of the nasal mucous membranes caused by an IgE-mediated response to external allergens. "A previous study showed that the number of T cells expressing TNFRSF1B was significantly higher in allergic rhinitis patients and that its expression was increased in nasal biopsies from allergic rhinitis patients as compared to control subjects." (PMID 32596360, 2020).
Hearing impairment (2 papers, 2014 to 2019). A decreased magnitude of the sensory perception of sound. "The present population-based cohort study demonstrated that TNF-α rs1800630 and TNFRSF1B rs1061624 contributed to the incremental risk of hearing impairment in the elderly." (PMID 25469152, 2014). "The present population-based cohort study demonstrated that TNF-α rs1800630 and TNFRSF1B rs1061624 contributed to the incremental risk of hearing impairment in the elderly Japanese population." (PMID 25469152, 2014). "The odds ratios for the hearing impairment (PTABE >25 dB) risk under additive genetic model were significant in TNF-α rs1800630 and TNFRSF1B rs1061624, which were respectively 1.172 (confidence interval [CI]: 1.005-1.367), 1.211 (CI: 1.053-1.392) in model after adjustment for possible confounders." (PMID 25469152, 2014). "Using the criterion of PTABE >40 dB as disabling hearing impairment, the association remains significant in TNFRSF1B rs1061624, but not in TNF-α rs1800630." (PMID 25469152, 2014).
neuropathy (2 papers, 2015 to 2021). A disorder affecting the nervous system that manifests with pain, tingling, numbness, and/or muscle weakness. "Previous studies have demonstrated an association of TNFRSF1B genotype with clinical neuropathy in T2DM." (PMID 35052752, 2021).
psoriatic arthritis (2 papers, 2022 to 2024). Joint inflammation associated with psoriasis. "In the JIA group, TNFRSF1B (TNFRII-TNFRSF1B) was significantly associated with a diagnosis of psoriatic arthritis (p < 0.050) according to the Benjamini–Hochberg procedure." (PMID 35217774, 2022). "Our data also show that a high concentration of TNFRSF1B in saliva was associated with a diagnosis of juvenile psoriatic arthritis (p = 0.004), but the association was based on a single individual, so no definitive conclusion can be drawn." (PMID 35217774, 2022).
pulmonary TB (2 papers, 2017 to 2021). "This study was designed to find out the impact of the variable number of tandem repeats (VNTR) of the tumor necrosis factor receptor 2 (TNFRSF1B) on pulmonary tuberculosis (PTB) risk in an Iranian population." (PMID 28447045, 2017).
selenium deficiency (2 papers, 2017 to 2021). A nutritional deficiency disease resulting from inadequate selenium levels in the body, which can lead to impaired function of selenoproteins essential for antioxidant defense and thyroid hormone metabolism. "This study is the first to report that the expression of TNFRSF1B mRNA and protein was induced by selenium deficiency in the broiler spleen." (PMID 28938575, 2017). "Reduced levels of microRNA-155 promoted apoptosis by targeting TNFRSF1B in the spleen tissues of broilers suffering from selenium deficiency." (PMID 28938575, 2017). "In this work, the levels of JNK mRNA and protein were increased with the increase in TNFRSF1B due to selenium deficiency." (PMID 28938575, 2017). "Interestingly, reduced expression of miR-155 promotes selenium deficiency-induced apoptosis by TNFRSF1B (tumor necrosis factor receptor superfamily member 1B) in the broiler spleen." (PMID 34210046, 2021). "Our results suggested that the up-regulation of TNFRSF1B due to selenium deficiency might indirectly stimulate JNK signaling to participate in the mitochondrial apoptotic process, but the detailed mechanisms need further study." (PMID 28938575, 2017).
uveitis (2 papers, 2022 to 2024). An inflammatory process affecting a part of or the entire uvea. "The ERAP1 rs2287987 AA genotype was more frequently observed in patients with enthesitis (AA vs. G+, p = 0.049), while the TNFRSF1B rs1061622 GG genotype was more common in participants with uveitis (GG vs. TT, p = 0.042)." (PMID 35629038, 2022). "The ERAP1 rs2287987 GG genotype was more frequently observed in patients with enthesitis, while the TNFRSF1B rs1061622 GG genotype was more common in participants with uveitis than the TT genotype." (PMID 35629038, 2022). "The GG genotype of TNFRSF1B rs1061622 was more common in patients with uveitis than the TT genotype (GG vs. TT, p = 0.042, OR = 5, 95% CI 1.08–20)." (PMID 35629038, 2022). "On the other hand, we showed a relationship between TNFRSF1B rs1061622 and uveitis." (PMID 35629038, 2022).
adenoma (1 paper, 2022). A neoplasm arising from the epithelium. "Some population studies have also shown that Tnfrsf1b increased with the increase of the adenoma-carcinoma sequence, and this change was correlated with tumor-associated microorganisms." (PMID 36118769, 2022).
age-related macular degeneration (1 paper, 2024). Age-related loss of vision in the central portion of the retina (macula), secondary to retinal degeneration. "In conclusion, identifying genetic variations in ARMS2, VEGFA, TNFRSF1A, TNFRSF1B, and IL1B1 provides valuable insights into the susceptibility to and treatment outcomes for age-related macular degeneration." (PMID 39273697, 2024). "In published databases, we did not uncover any studies examining the serum correlations of TNFRSF1A, TNFRSF1B, and IL1B1 with age-related macular degeneration." (PMID 39273697, 2024).
arteriosclerosis (1 paper, 2017). A vascular disorder characterized by thickening and hardening of the walls of the arteries. "TNFRSF1B was found to play a significant role in the initiation and progression of arteriosclerosis and promotes adaptive arteriogenesis and angiogenesis." (PMID 27791988, 2017).
chordoma (1 paper, 2022). Chordomas are rare malignant tumors arising from embryonic remnants of the notochord in axial skeleton. "We observed significant overexpression of TNF family members and several TNF receptors (TNFRSF1B/4/8/18) in the chordoma samples (data not shown)." (PMID 36033338, 2022).
cutaneous melanoma (1 paper, 2024). A primary melanoma arising from atypical melanocytes in the skin. "We aimed to examine the effects of single nucleotide variants TNFRSF1B c.587T>G, c.*188A>G, c.*215C>T, and c.*922C>T on the clinicopathological characteristics and survival of cutaneous melanoma (CM) patients." (PMID 38474115, 2024).
Headache (1 paper, 2025). Cephalgia, or pain sensed in various parts of the head, not confined to the area of distribution of any nerve. "Genetically, CD302 was associated with headache (P = 2.60 × 10−5), RARRES2 was associated with neck or shoulder pain (P = 3.94 × 10−4), TNFRSF1B was associated with back pain (P = 7.96 × 10−5), and CD74 was associated with hip pain (P = 3.21 × 10−4)." (PMID 40048323, 2025).
medulloblastoma (1 paper, 2025). A malignant, invasive embryonal neoplasm arising from the cerebellum. "All immune cells express receptors for TNF-alpha (TNFRSF1A and TNFRSF1B) and IFN alpha (IFNAR1 and IFNAR2) and are enriched for these pathways, indicating that all these immune cell types are primed to respond to secreted TNF-alpha and IFN alpha in the medulloblastoma TME." (PMID 40240536, 2025).
peripheral T-cell lymphoma (1 paper, 2024). "The TNF receptor superfamily member 1B (TNFRSF1B), TNFRSF1A linked by the death domain TRADD, and TRAF1 associated with TNF receptors are inhibited in peripheral T-cell lymphoma when chemotherapy resistance occurs." (PMID 38468267, 2024). "Our study revealed that the expression of specific genes, including TNFRSF1B, TRADD2, and MAP3K7, may play an important role in chemotherapy resistance in peripheral T-cell lymphoma." (PMID 38468267, 2024).
pneumonitis (1 paper, 2010). An inflammatory process affecting the lung parenchyma. "Genetic variation in TNF and the receptor TNFRSF1B were also associated with increased risk of pneumonitis." (PMID 20811626, 2010).
thyroid cancer (1 paper, 2023). "However, to our knowledge, no study has shown the differences in TNFRSF1B (encoding TNFR2) methylation (and thereby expression of TNFR2) dependent on BRAF mutation status in thyroid cancer." (PMID 36975440, 2023).
tumor (294 papers, 2008 to 2026). "TNFRSF1B antibody caused a pronounced suppression effect on tumour growth after five treatments, lower tumour volume and tumour weight at the endpoint were observed in the subcutaneous tumour model." (PMID 37712139, 2023). "Tnfrsf1b was discovered to be associated with not only cecal tumor weights and liver metastatic area, but also Lactobacillus helveticus." (PMID 36118769, 2022). "The variants in EXOG, RANBP2, RANBP6 and TNFRSF1B were sequenced in the tumour DNA of P1 to assess which allele of the gene was lost." (PMID 32357859, 2020). "Therefore, the good prognosis and anti‐tumour functions caused by blocking TNFRSF1B are the result of a variety of cells." (PMID 37712139, 2023). "Among these immune-associated ligands and receptors, CTLA4, CCR5 and CSF1R could contribute to tumor immune suppression, while TNFRSF1B and type II IFNR are associated with stimulation in neutrophils." (PMID 36443332, 2022). "Taking CD4+ Treg cells and CD8+ cytotoxic T cells as examples, Treg cells derived from tumor tissues showed higher expression of LAYN, LGALS1 and TNFRSF1B, and cytotoxic T cells derived from tumor tissues showed higher expression of TNFRSF9 (encoding 4-1BB), LAYN and CTLA4." (PMID 36104333, 2022). "The missense variants in EXOG, RANBP6 and TNFRSF1B remained heterozygous in the primary tumour of P1, although with the loss of the second allele at a later stage, this does not necessarily exclude these variants as possible PMP predisposition genes on these data alone." (PMID 32357859, 2020). "Compared to Treg.1, Treg. showed significantly up-regulated genes (TNFRSF4/OX40, TNFRSF18/GITR, TNFRSF9/4–1BB, TNFRSF1B/TNFR2 and LAIR2) associated with suppressive functions of tumor-infiltrating Tregs49." (PMID 39803458, 2025). "High TNFRSF1B (TNFR2) expression in tumor‐infiltrating Tregs; TNFR2 inhibition reduces immune‐related adverse events while maintaining ICB efficacy (TIL中Treg的TNFRSF1B)." (PMID 40529611, 2025). "Based on above three diagnostic markers, we developed a diagnostic nomogram for TNBC patients, which showed that patients with high expressions of CD86, TNFRSF17, and TNFRSF1B had a high probability of “hot” tumor." (PMID 39007147, 2024). "TNFRSF1B encodes the receptor for tumor necrosis factor-α (TNFR2), which plays a crucial role in promoting tumor growth, invasion, and metastasis." (PMID 37108754, 2023). "Blockade of TNFRSF1B inhibited tumour growth by profoundly remodelling the immune microenvironment in the OC mouse model." (PMID 37712139, 2023). "For the subcutaneous tumour model, IgG isotype control antibody and anti‐TNFRSF1B antibody was injected intraperitoneally every 6 days, and the tumour volume was measured on day 5, 9, 12, 18, 24 and 30 after ID8 injection." (PMID 37712139, 2023). "To determine the antitumor effect of TNFRSF1B in vivo, we used a syngeneic subcutaneous tumour model and a metastatic OC model was used." (PMID 37712139, 2023). "Blockade of TNFRSF1B inhibits tumour growth by profoundly remodelling the immune microenvironment in OC mouse models." (PMID 37712139, 2023). "In our study, we found that in tumor tissue from the BRAF mutant group, TNFRSF1B (encoding TNFR2) was significantly hypomethylated, suggesting potential overexpression of TNFR2 in this group of patients." (PMID 36975440, 2023). "Our scRNA‐seq data revealed a high expression pattern of TNFRSF1B in both tumour Tregs and exhausted T cells." (PMID 37712139, 2023). "The in vivo imaging of tumours from mice with intraperitoneal injection demonstrated 100% metastatic tumour growth in control mice but 20% (1/5) in mice after being treated with anti‐TNFRSF1B antibodies." (PMID 37712139, 2023). "In particular, Tnfrsf1b-mediated activation of CTLs showed tumor regression in syngeneic EMT6 models." (PMID 35651625, 2022). "Results revealed that high FAS, TNFRSF14, TNFRSF17, TNFRSF1B, and TNFSF13B expressions are associated with a high probability of “hot” tumor." (PMID 36588791, 2022).